FBLN5 (fibulin 5)
Diseases named in the same sentence as FBLN5 in open-access papers (continued):
Sharing a sentence is not in itself a finding about the gene and the disease.
tumor (47 papers, 2013 to 2026). "As tumor suppressor genes, fibulin-2 and fibulin-5 were widely considered to be associated with the suppression of tumor growth, invasion, and angiogenesis." (PMID 25885889, 2015). "No earlier studies on fibulin-4 had reported an association with tumor angiogenesis, although its highly homologous proteins, fibulin-3 and fibulin-5 were found to be associated with tumor angiogenesis." (PMID 25885889, 2015). "The high expression of FBLN5 might be closely related to the infiltration of immunosuppressive cells, such as CAFs, tumor-associated macrophages (TAMs), and dendritic cells." (PMID 36672502, 2023). "In primary tissues, FBLN5 expression was higher in tumor samples compared with normal tissue, as shown by western blot analysis." (PMID 40369121, 2025). "This pattern observed in paired hematoxylin and eosin (H&E) and IHC staining suggests localized secretion and diffusion of FBLN5 within the tumor microenvironment." (PMID 40369121, 2025). "Among other downregulated genes notable is Fbln5, whose expression correlates significantly with the infiltration of various immune cells into the tumour, including CD4+ T cells, M0 and M2 macrophages." (PMID 40547518, 2025). "FBLN5 has also been shown to have tumor-suppressive effects in gastric cancer, breast cancer, and lung cancer." (PMID 39334363, 2024). "FBLN-5 can inhibit tumor cell movement and proliferation through integrin-dependent mechanism, and its downregulation is significantly associated with advanced cancer cell metastasis." (PMID 38568089, 2024). "Next, we compared the expression of FBLN5 in tumor tissues and healthy tissues adjacent to the tumor in the training cohort and found that FBLN5 was expressed at relatively high levels in cancer cells." (PMID 36672502, 2023). "We analyzed the relationships between the expression levels of FBLN5 and the tumor immune microenvironment." (PMID 36672502, 2023). "We found that FBLN5 not only played an important role in the tumor microenvironment, but also served as a potential marker for tumor-related fibroblastogenic prognosis." (PMID 36672502, 2023). "Patients with high FBLN5 expression levels were more inclined to exhibit the INFc tumor infiltration pattern and N3 stage." (PMID 36672502, 2023). "In recent years, the number of studies on the roles of FBLN5 in tumor processes have increased significantly." (PMID 36672502, 2023). "Numerous studies have shown that FBLN5 acts as an inhibitor or promoter of tumor cell growth depending largely on the cancer type and environment." (PMID 36672502, 2023). "In well-differentiated adenocarcinoma, FBLN5 was highly expressed in the cytoplasm of cancer cells and tumor interstitial fiber cells." (PMID 36672502, 2023). "FBLN5, an extracellular matrix protein, takes part in regulating the proliferation, invasion and angiogenesis of malignant tumor cells." (PMID 35543375, 2022). "Immunohistochemically, there was a reduction in Ki67 and an increase in FBLN5 in UBE2T shRNA-treated tumor tissues." (PMID 35543375, 2022). "In in vivo experiments, it was found that UBE2T knockdown inhibits the tumor growth in accumulating evidence has shown that that FBLN5, as a tumor suppressor, has LUAD." (PMID 35543375, 2022). "Fibulin-5 (Fbln5), a matricellular protein typically expressed by stromal cells and acts as a tumor promoter by blocking fibronectin-mediated integrin signaling and directly limiting ECM-driven ROS generation." (PMID 33436044, 2021). "The core dynamic DEGs (Mnda, Cyp1b1, Comp, Phex, Mmp3, Tnfrsf1b, Fbln5, and Nfkb2) had been reported to be closely related to the development and metastasis in tumor and cancer progress." (PMID 33042984, 2020). "Fibulin-5 is downregulated in several human cancers and has a tumor-suppressive function mediated through its interaction with matrix metalloproteinases." (PMID 32887625, 2020).
tumor (continued). "Fbln5 can inhibit epithelial cell proliferation and carries out tumor-promoting and tumor-protective functions in breast lesions." (PMID 33042984, 2020). "This work indicates that FBLN5 is degraded in EOC most likely by proteases enriched in macrophages of the tumor microenvironment." (PMID 29581841, 2018). "We considered possible proteases that degrade FBLN5 and would thereby prevent the tumor suppressive functions of FBLN5." (PMID 29581841, 2018). "In summary, we found dramatic upregulation of MMP7 and FBLN5 degradative products in tumor macrophages of EOC." (PMID 29581841, 2018). "Hypermethylation of Fibulin-5 promoter has been identified in several histologically normal tissues surrounding the tumours." (PMID 30305430, 2018). "CD68+ tumor macrophages were distributed throughout the tumor and the stromal compartment, both of which were positive for FBLN5." (PMID 29581841, 2018). "Because A549 and H1299 cells do not form lung metastasis, we used H460 and H1752 cells to analyze the effect of fibulin-5 on tumor metastasis." (PMID 25909283, 2015). "The anti-tumor effect of fibulin-5 is mediated through tumor microenvironment and suppression of MMP-7, which is overexpressed in NSCLC and associated with poor prognosis." (PMID 25909283, 2015). "Xenograft tumor models were used to further determine the role of fibulin-5 in suppressing lung tumor growth in vivo." (PMID 25909283, 2015). "Further, FBLN5 was predominantly located in the stroma with a gradient from the periurethral to the peripheral zone, and silenced in tumor tissues." (PMID 23593148, 2013). "In addition, after Chi-square analysis, we found that the expression level of FBLN5 was related to the tumor infiltration pattern and N stage." (PMID 36672502, 2023). "Moreover, five genes, including the SLC12A4, SLIT3, GYPC, TSPAN4, CYYBRD1, CYB5R3, and FBLN5 were identified as co-expressed in the healthy and tumor tissue groups." (PMID 37365287, 2023). "The FBLN5 expression level in patients showed an increasing trend with an increase in tumor progression, lymph node metastasis, and pTNM stage, and the patient prognosis was poor, which suggests that FBLN5 might be a biomarker of tumor progression." (PMID 36672502, 2023). "This showed that FBLN5 was closely related to the tumor microenvironment and could promote tumor metastasis through various methods." (PMID 36672502, 2023). "Hence, the mechanisms of action of FBLN5 in various tumors need to be analyzed according to different tumor types." (PMID 36672502, 2023). "However, FBLN5 was highly expressed in another poorly differentiated adenocarcinoma, suggesting that there is heterogeneity in the expression levels of FBLN5 in tumor cells with the same degree of differentiation." (PMID 36672502, 2023). "TGF-β initiated pathological carcinogenic EMT processes during fibrosis and tumor formation, which confirmed that FBLN5 might play an important role in tumor progression." (PMID 36672502, 2023). "Being a secreted protein, FBLN5 offers prospects for tumour-specific protein therapy." (PMID 37864183, 2023). "FBLN5 is highly expressed and closely related to malignant clinicopathological factors, including poor differentiation, lymph node metastasis, and high tumor stage in GC, indicating FBLN5 exhibits tumor-promoting effects in GC." (PMID 37644092, 2023). "LINC01089 exerts a tumor suppressor effect by up-regulating the level of FBLN5." (PMID 36306007, 2022). "In addition, in BC cells and tumor tissues, FBLN5 expression downregulates the activation of the NF-κB signaling pathway to promote BC cell proliferation and migration." (PMID 36531485, 2022). "It is possible that tumor macrophages, or peritoneal cells, may mediate FBLN5 degradation in EOC tumors." (PMID 29581841, 2018). "We hypothesized that intact FBLN5 may either inhibit tumor cell-derived MMP-9 or inhibit malignant cell adhesion to native ECM components and thereby protect from local spread of the disease." (PMID 29581841, 2018).
tumor (continued). "TGF-β can also induce fibulin 5 (FBLN5), which promotes tumor invasion and epithelial-mesenchymal transition (EMT) by elevating Twist1 transcription and reducing E-cadherin expression, although the precise mechanism by which FBLN5 regulates Twist1 transcription remains elusive." (PMID 28099910, 2017). "Since fibulin-4 is highly homologous to fibulin-3 and fibulin-5, we speculate that fibulin-4 may play a significant role in tumor angiogenesis." (PMID 25885889, 2015). "However, several studies showed tumor-promoting activity of fibulin-5, suggesting cell type- and context-dependent functions of fibulin-5 in cancer." (PMID 25909283, 2015). "Fibulin-5 also blocks Wnt/β-catenin signaling in vivo in H460 metastasis and H1299 tumor models." (PMID 25909283, 2015). "Similar to the other types of fibulins, fibulin-5 may also promote or inhibit tumor progression." (PMID 34063320, 2021). "In the fibrotic stroma of DGC, CAF-derived FBLN5 promotes EMT through the downstream CREB pathway and is secreted into bloodstream, where it correlates with expression in primary tumor tissue." (PMID 40369121, 2025). "Taken together, these findings indicate that interaction between CAF-derived fibulin-5 and its influence on the EMT and aggressiveness of DGC is mediated through the CREB signaling pathway within the tumor microenvironment, as shown in an overview." (PMID 40369121, 2025). "Fibulin-5 expression levels strongly correlated with survival outcomes in patients with DGC, even after adjusting for confounding variables, including tumor stage." (PMID 40369121, 2025). "Studies have noted that overexpression of fibulin-5 (FBLN5) suppresses DNA synthesis and cyclin A expression in mink lung epithelial cells, thus suppressing tumour cell proliferation." (PMID 37325048, 2023). "FBLN5 is also a target of TGF-β in fibroblasts and endothelial cells, which affect tumor progression." (PMID 36672502, 2023). "Events related to a single gene, such as WNK1,FBLN5 and RACGAP1, exhibited opposite patterns between tumor and normal samples, indicating that an uneven distribution in the splicing patterns plays different roles in cancer development." (PMID 34130646, 2021). "FBLN5 was silenced by promoter hypermethylation, and this resulted in activation of MMP7 and increased tumor invasion." (PMID 29581841, 2018). "In that study, FBLN5 protein expression correlated with poor differentiation and advanced TNM tumor stage." (PMID 27941907, 2016). "In line with reduced tumor growth, expression of p-ERK, nuclear β-catenin, c-Myc and MMP-7 was found to be substantially decreased in fibulin-5-expressing H1299 tumors, compared to the parental H1299 tumors lacking fibulin-5 expression." (PMID 25909283, 2015). "Meanwhile expression of gene DPT, SMOC2, GLP2R, FBLN5 and LMOD1 were down-regulated in tumor tissues." (PMID 25970782, 2015). "Microscopic images for FBLN5 in AGC tissues showed a gradient of expression from tumor to adjacent non-tumor tissues." (PMID 40369121, 2025). "In addition, patients with high FBLN5 expression levels had higher immune scores, stromal scores, and ESTIMATE scores, ans well as lower tumor purity." (PMID 36672502, 2023). "Even more, Kaplan-Meier survival curves of progression-free survival (PFS) demonstrated inferior survival probabilities in patients with high tumor expression of PXDNL (p=0.0001) and SDC1 (p<0.0001) and low tumor expression of FBLN1 (p=0.0087), FBLN5 (p=0.026) and ADAMTS8 (p<0.0001)." (PMID 37056938, 2023). "Similarly, morbidity or mortality, necrosis, necrosis of tumour and organismal death were predicted to be inhibited upon SV40 transformation whereas the same processes were predicted to be activated when FBLN5 was experimentally overexpressed in COS-7 cells." (PMID 37864183, 2023). "Therefore, we preliminarily analyzed the regulatory effect of NDUFS1 on FBLN5 in NDUFS1-overexpressing and -interfering GC cells and their tumor xenografts." (PMID 37644092, 2023).
tumor (continued). "In addition, the high-expression group had a higher estimate score, immune score, stromal score, and lower tumor purity (ALL p < 0.05), which indicate that FBLN5 has a significant effect on the immune status of the tumor microenvironment." (PMID 36672502, 2023). "In addition, MAGEC3 downregulates genes that are shown to induce tumor progression, including APLMR, FBLN5, and FNDC1." (PMID 35158998, 2022). "The sub‐clustering of ECs revealed six subtypes, including extra‐alveolar capillary EC (cEC) (FCN3+EDN1+PLVAP+), alveolar cEC (HPGD+EDNRB+IL1RL1+), arterial EC(GJA5+FBLN5+DKK2), lymphatic EC (CCL21+TFF3+FABP4), INSR+ tumour EC (INSRhiHSPG2+PLVAP+), and ACKR1+ tumour EC (ACKR1+SELP+IL1R1+)." (PMID 35184398, 2022). "At the protein level, 66 kDa FBLN5 protein was identified as two additional immunoreactive species, 53 kDa and 41.2 kDa in malignant tissues which were immunoreactive in tumor macrophages, not cancer cells or stroma." (PMID 29581841, 2018). "Recombinant FBLN5 significantly inhibited adhesion of EOC cells to both laminin and collagen I. Finally, using immunohistochemistry, we found immunoreactive FBLN5 within tumor macrophages throughout human EOC tumors." (PMID 29581841, 2018). "In our studies, degradation of FBLN5 appeared to be independent of tumor cells in culture or tissue extracts." (PMID 29581841, 2018). "Fibulin-5 also inhibited transactivation of the TOPFlash reporter by wild-type (WT) β-catenin, and that by a tumor-derived mutant β-catenin lacking the amino-terminal phosphorylation sites (ΔN) required for its degradation." (PMID 25909283, 2015). "This phenomenon is not without precedent, since other tumor types have demonstrated context-specific expression of fibulin family members such as the expression of Fibulin-5." (PMID 23840707, 2013). "FR exhibited a high level of basement membrane proteins and fibroblast lineage markers (COL4A1, FBLN5, DCN, DPT) and is enriched for ECM organization, wound-healing, and cell adhension pathways, suggesting a potential shared mechanism between tumor-surrounding stroma and tissue repair." (PMID 39870619, 2025). "Nonetheless, this result does not rule out the possibility that FBLN5 may suppress MMP-9 generated in tumor stroma or macrophages." (PMID 29581841, 2018). "Stromal fibroblasts and tumor cells were negative for FBLN5." (PMID 29581841, 2018). "Thus, depending on tumor type, FBLN5 may either promote or inhibit tumor growth through mechanisms that are not totally understood." (PMID 27941907, 2016).
cancer (20 papers, 2015 to 2025). A tumor composed of atypical neoplastic, often pleomorphic cells that invade other tissues. "They discovered that FBLN5, produced by cells called cancer-associated fibroblasts, helps cancer cells spread by promoting the epithelial–mesenchymal transition process." (PMID 40369121, 2025). "Among the novel anticancer genes, FBLN5, encoding a secreted glycoprotein belonging to a small but versatile family of secreted extracellular matrix proteins known as fibulins, has a role in numerous cancers." (PMID 37864183, 2023). "Altered expression and function of fibulin 5 has been implicated in several human cancers." (PMID 29581841, 2018). "Among the six DASCs, FBLN5 was shown to have a prognostic impact through TMA analysis of over 280 patients with cancer, incorporating detailed clinical information and survival data." (PMID 40369121, 2025). "For FBLN5, cancer cases were categorized into FBLN5Low and FBLN5High groups based on the intensity of IHC staining in TMA tissues, and survival analyses were performed accordingly." (PMID 40369121, 2025). "IF staining of paired normal and cancer tissue samples also revealed high FBLN5 expression in cancer tissues, whereas expression was minimal in normal tissue." (PMID 40369121, 2025). "The results indicated that CAF-derived FBLN5 significantly facilitates the migratory behavior of cancer cells." (PMID 40369121, 2025). "The TECs3 subtype, characterized by FBLN5 and TMEM100 expression, was linked to the EMT, a process that has been implicated in increased motility and invasiveness of many cancer types and contributes to metastasis." (PMID 40123905, 2025). "Culture media withdrawn from the co-culture system showed significantly higher concentrations of fibulin-5 compared with the media from the cancer cell monoculture system." (PMID 40369121, 2025). "The probable pathway within cancer cells induced by secreted fibulin-5 is the CREB–GSK-3αβ pathway, based on results from the phosphokinase array and other supporting experiments in the present study." (PMID 40369121, 2025). "In order to verify the effect of FBLN5 on GC prognosis, we performed IHC staining of FBLN5 using the histological chip, and the staining results showed that FBLN5 was mainly expressed in the cytoplasm of cancer cells and interstitial fibrous cells of tumors." (PMID 36672502, 2023). "FBLN5 has cancer-promoting effects in some tumors, cancer-suppressive effects in some tumors, and supports targeted therapy in some tumors while supporting immunotherapy in some tumors." (PMID 36672502, 2023). "In individuals with ovarian cancer, FBLN5 induces cell cycle arrest and regulates the expression of cell-cycle-related proteins, thereby inhibiting the progression and metastasis of cancer cells." (PMID 36672502, 2023). "We simultaneously evaluated FBLN5 expression levels and immune cell invasion in various types of cancer using TIMER and CIBSCORE analyses." (PMID 36672502, 2023). "This suggests that FBLN5 was closely related to the RGD motif-integrin/MAPK axis during the process of promoting cancer cell metastasis." (PMID 36672502, 2023). "Abundant proteins localized mainly in the ECM, which are known EMT activators (e.g., collagen 1, fibulin 5), or promoters (transgelin) in different human cancers, were observed." (PMID 34572331, 2021). "A hypothesis is that fibulin-5 binds to integrins on cancer cells and triggers the downstream CREB pathways." (PMID 40369121, 2025). "Of these, FBLN5 is an anti-oncogene that belongs to the family of fibulins, and its aberrant expression has been reported in lung, breast, hepatocellular, and other types of cancer." (PMID 36980682, 2023). "The abnormality of FBLN5 is also closely related to the occurrence and development of cancer." (PMID 37644092, 2023). "FBLN5, as a member of the fibrin family, regulates important biological processes related to cancer occurrence and development and has been proven to play an important role in a variety of cancers." (PMID 36672502, 2023).